ATR (ATR checkpoint kinase)
Diseases named in the same sentence as ATR in open-access papers (continued):
Sharing a sentence is not in itself a finding about the gene and the disease.
ovarian carcinoma (continued). "Notably, treatment with an ATR inhibitor abolished DDUP-induced DNA damage repair and protection against apoptosis, leading to the development of CDDP-resistant ovarian cancer cells that were more vulnerable to platinum-based chemotherapeutic agents." (PMID 37633920, 2023). "Our results showed that ADAR1 knockdown caused increase of phosphorylation of Chk1 and ATR, but not phosphorylation of Chk2 and ATM, indicating that single strand DNA was generated by ADAR1 knockdown in ovarian cancer cells." (PMID 35711824, 2022). "Hence, it's a good strategy to explore combination ATR inhibitor and ADAR1 inhibitor for ovarian cancer treatment in future studies." (PMID 35711824, 2022). "Since the addition of ATR inhibition to CHK1 inhibition is known to induce DNA replication catastrophe in cancer cells, we decided to further evaluate the impact of ATRi-CHK1i in the ovarian cancer cells, specifically at low doses." (PMID 36381271, 2022). "The effect of ATR and CHK1 kinases in response to PARPi treatment on cell cycle disorders and its consequences in ovarian cancer cells remain unclear." (PMID 35741017, 2022). "In the chemotherapy-resistant ovarian cancer preclinical model, we investigated whether AZD6738 (an ataxia telangiectasia and Rad3-related (ATR) inhibitor) could synergize with belotecan (a camptothecin analog and topoisomerase I inhibitor)." (PMID 33513721, 2021). "Indeed, the combined inhibition of ATR and PARP was able to overcome platinum and PARP inhibitor resistance in patient-derived xenografts models of ovarian cancer." (PMID 34976801, 2021). "Additionally, increased ATR protein, phospho-ATR, and phospho-CHK1 expression confers a poor prognosis in breast, bladder, and ovarian cancers." (PMID 35366284, 2021). "Inhibitors of ATR and CHK1 are therefore promising drugs for ovarian cancer treatment." (PMID 32316968, 2020). "Amplification of ATR and CHK1 genes was noted in ovarian cancers with genomic instability." (PMID 31018854, 2019). "FMR1 may be involved in the regulation of ATR-dependent signaling pathways such as BRCA1 phosphorylations and interact with BRCA in human Ovarian Cancers." (PMID 30286182, 2018). "In particular, cells can become sensitized to cisplatin after ATR depletion; a recent report shows that CDK6 regulates transcription of ATR, and that CDK6 inhibition therefore sensitizes epithelial ovarian cancer cells to death from cisplatin due to an impaired DNA damage response." (PMID 29644000, 2018). "ATR inhibitors NU6027 and VE-821 have been shown to increase the cytotoxic activity of PARP inhibitors (rucaparib and veliparib) in two BRCA wild-type cancer cell lines and various ovarian cancer cell lines." (PMID 28448462, 2017). "We here report the retrospective analysis of 7 polymorphisms in 5 genes involved in the cellular response to cisplatin (DDP): ATM, ATR, Chk1, Chk2 and CDK12 in a cohort of 240 cancer patients with stage III/IV ovarian cancer underwent surgery and adjuvant chemotherapy." (PMID 27905519, 2016). "Altogether, this study underscores the promise of combining PARP inhibitors with ATR/CHK1 pathway inhibition to reduce OC cell viability and invasiveness, potentially overcoming the limitations of single-agent therapies in the treatment of epithelial ovarian cancer." (PMID 39859407, 2025). "Notably, treatment with an ATR inhibitor disrupted the DDUP/RAD18 interaction and abolished the effect of DDUP on prolonged DNA damage signaling, which resulted in the hypersensitivity of ovarian cancer cells to cisplatin-based therapy in vivo." (PMID 37633920, 2023). "Notably, elevated baseline levels of activated ATR and CHK1 have been detected in several PARP-inhibitor-sensitive ovarian cancer cells, indicating a high level of preexisting RS that made these cells highly dependent on the ATR/CHK1 pathway with increased sensitivity to ATR inhibitor therapy." (PMID 36253861, 2022).
ovarian carcinoma (continued). "Therefore, NUSAP1 in ovarian cancer may participate in HRR by regulating the levels of ATR and BRCA1/2; thus, low expression of NUSAP1 in ovarian cancer implies sensitivity to PARP inhibitors." (PMID 35739489, 2022). "Importantly, both ALDH knockout and 673A treatment of ovarian cancer cell lines synergized with DNA damage checkpoint inhibitors, AZD1390 (ATM inhibitor) and AZD6738 (ATR inhibitor), resulting in a synergistic decrease in cell viability in vitro and tumor growth in vivo." (PMID 33664846, 2021). "Further clinical investigation of the PARP inhibitor/ATR inhibitor combination has been extended to multiple phase 2 trials, including the VIOLETTE study on TNBC, the SUKSES-N2 study on small-cell lung cancer (NCT03428607), and the CAPRI study on ovarian cancer (NCT03462342)." (PMID 31018854, 2019). "Thus, in this study, we investigated the role of ATR and CHK1 inhibition at the early stage of olaparib response in BRCA2MUT (PEO-1) and BRCAWT (OV-90 and SKOV-3) ovarian cancer cells and sought to further elucidate the mechanisms leading to ovarian cancer cell death." (PMID 35741017, 2022). "This principle of “ATR dependency” is not unique to NSCLC; it also explains the outcomes observed in specific subgroups of ovarian cancer." (PMID 41409249, 2025).
Seckel syndrome (87 papers, 2005 to 2025). A rare autosomal recessive inherited syndrome caused by mutations in the ATR gene, RBBP8 gene, CENPJ gene, CEP152 gene, CEP63 gene, NIN gene, DNA2 gene, or TRAIP gene. "Paradoxically, the human Seckel syndrome caused by ATR mutations exhibits premature aging and neuropathies, suggesting a role of ATR in nonreplicating tissues." (PMID 40105243, 2025). "The essentiality of the ATR-mediated replication stress response is highlighted by the embryonic lethality observed under ATR deficiency, as well as the severe developmental disorder Seckel syndrome caused by ATR hypomorphism." (PMID 39859385, 2025). "Mutations in ATR are linked to Seckel syndrome characterized by severe microcephaly, growth retardation, and increased cancer risk." (PMID 39951537, 2025). "A partial deficiency of ATR leads to devastating neurological consequences that include microcephaly and mental retardation, a disorder known as Seckel syndrome." (PMID 39085642, 2024). "Constitutional homozygous or compound-heterozygous hypomorphic variants of ATR cause Seckel syndrome (MIM #210600), characterized by intrauterine growth retardation and primordial dwarfism, with marked microcephaly." (PMID 36749285, 2023). "Due to the plausible role of ATR in mammalian cell DNA integrity, mutation rates in this gene are quite low, with the exception of a rare genetic syndrome, the Seckel syndrome, which is characterized by biallelic ATR mutations." (PMID 36769087, 2023). "In this mouse model, a hypomorphic mutation of ATR, similar to the mutation that causes Seckel syndrome in humans, is present, resulting in a profound decrease in ATR activity." (PMID 37511442, 2023). "This indicated that the reduced cellularity caused by ADSL depletion occurs in a manner mechanistically distinct from Seckel syndrome driven by ATR deficiency or centrosome duplication defects." (PMID 35133277, 2022). "The fact that mutations causing Seckel syndrome are hypomorphic, with only a partial loss of gene function, and that ATR knockout mice are embryonic lethal further implies that ATR is an essential gene." (PMID 35008191, 2021). "Although biallelic loss of ATR is early embryonic lethal and hypomorphic ATR mutations produce Seckel syndrome with severe microcephaly and growth retardation; ATR inhibitors are surprisingly well-tolerated in patients." (PMID 34572827, 2021). "In adult mice, ATR depletion causes a premature aging-like syndrome that has been attributed to stem cell loss and appears akin to Seckel syndrome, a complex form of microcephalic primordial dwarfism that occurs in humans with ATR gene mutations." (PMID 34422791, 2021). "Ataxia Telangiectasia and Rad3-related (ATR) is a key regulator of replication stress response; yet, mutations within the ATR gene cause human ATR-Seckel Syndrome associated with microcephaly and intellectual disability." (PMID 34210973, 2021). "For example, mutations in the Ataxia Telangiectasia and Rad3-related (ATR) gene can cause Seckel syndrome (microcephalic primordial dwarfism), characterised by microcephaly and intellectual disability." (PMID 33744934, 2021). "ATM and DNA-PK genes are mutated in various Mendelian genetic diseases, while germline mutations affecting ATR have been linked to only one hereditary disorder, Seckel syndrome." (PMID 35008191, 2021). "Mutations in Ataxia Telangiectasia and Rad3-related (ATR) or in ATR-interacting protein (ATRIP) lead to Seckel syndrome, which is characterized by developmental malformations and short life expectancy." (PMID 33110058, 2020). "Hypomorphic mutations of ATR, like the splicing mutation A2101G that leads to extremely low levels of the protein, underlie a subset of Seckel syndrome patients with craniofacial abnormalities, microcephaly, and growth retardation." (PMID 32015826, 2020). "Previously, defects in the ATR gene were found to cause Seckel syndrome 1, a premature aging disease." (PMID 32687062, 2020).
Seckel syndrome (continued). "Among these genes are those coding for the protein kinases ATM (Ataxia-telangiectasia mutated) and ATR (Ataxia telangiectasia and Rad3-related), mutated in the genetic-instability syndromes Ataxia Telangiectasia and Seckel syndrome, respectively." (PMID 30995915, 2019). "Taken together, our data combined with previously published observations suggest that ATR-Seckel Syndrome is frequently caused by mutations, either exonic or intronic, that disrupt gene splicing." (PMID 30199583, 2018). "In this work, we have characterized two novel compound heterozygous ATR mutations in a Seckel Syndrome patient." (PMID 30199583, 2018). "Seckel syndrome is caused by mutations in DNA damage response signaling and centriole biogenesis factors (ATR, ATRIP, CEP152, CENPJ)." (PMID 28630177, 2017). "Hypomorphic mutations in ATR have been linked to Seckel syndrome in humans, a disease characterized by severe growth retardation, microcephaly, and facial and osteoskeletal abnormalities." (PMID 26695548, 2016). "As expected, LWAS identified ATR as the highest-ranking gene associated with Seckel Syndrome, mainly based on explicit links (direct co-occurrences in seven Medline abstracts)." (PMID 26919047, 2016). "The highest ranking concepts for the implicit association of RBBP8 and Seckel Syndrome were ATR and cell cycle checkpoint." (PMID 26919047, 2016). "In contrast to ATR, many other characterized genetic defects for SS as well as those for related disorders conferring microcephalic primordial dwarfism (MPD) are found in centrosomal proteins or those that cause centrosomal defects." (PMID 26908596, 2016). "For example, the DNA damage activated protein kinases ATM and ATR (paralogs of DNA-PK) are mutated in ataxia-telangectasia and ATR-Seckel syndrome, respectively." (PMID 26500484, 2015). "It is interesting to compare this observation with Seckel syndrome, the human disease associated with ATR mutation." (PMID 24675793, 2014). "Seckel syndrome results from the hypomorphic effect of inheriting a single ATR mutation, which consequently reduces ATR function and is characterized by severe microcephaly and proportional primordial dwarfism and skeletal abnormalities." (PMID 24675793, 2014). "Hypomorphic mutations in human ATR cause the rare autosomal-recessive disease Seckel syndrome, and complete loss of Atr in mice leads to embryonic lethality." (PMID 24675793, 2014). "This includes mutations in the DNA damage response kinase ATR as a cause of Seckel syndrome and PCNT mutations, which have been identified in MOPDII." (PMID 24711643, 2014). "Our observation that ATRi renders SV40 fork convergence prone to DNA breakage is reminiscent of common fragile sites in the human genome, which suffer gaps and breaks in Seckel Syndrome cells that express defective ATR alleles." (PMID 23592994, 2013). "ATR deficiency is lethal in mammalian cells but hypomorphic atr mutations have been described in a few patients with the rare Seckel syndrome, characterized by microcephaly and growth retardation." (PMID 24137170, 2013). "Hypomorphic mutations in the ATR gene can cause the genomic instability disorder Seckel Syndrome, but complete loss of ATR results in cell death." (PMID 23592994, 2013). "Mutations in ATR, which also functions during replication, can cause Seckel syndrome, a clinically related disorder." (PMID 23516378, 2013). "Coupled with the identification of further ATR–deficient patients, our findings allow a spectrum of clinical features that can be ascribed to the ATR–ATRIP deficient sub-class of Seckel Syndrome." (PMID 23144622, 2012). "Cells from patients with Seckel syndrome, who express low levels of ATR protein due to a hypomorphic mutation in the ATR gene, exhibit an increase in chromosomal breakage at common fragile sites compared to unaffected individuals." (PMID 21286310, 2010). "In humans, the autosomal recessive disorder known as Seckel syndrome (MIM #210600) is associated with ATR mutation." (PMID 21054854, 2010).
Seckel syndrome (continued). "Loss of ATR in mice results in embryonic lethality whereas hypomorphic mutations in the ATR gene have been identified in a few patients with the Seckel syndrome." (PMID 19008195, 2009). "Mutations in ATR result in Seckel syndrome, a disorder characterised by microcephaly and growth retardation." (PMID 19440510, 2008). "Recently, inherited defects in ATR signalling were shown to associate with Seckel syndrome, because patients in two families were found to be homozygous for a hypomorphic ATR mutation." (PMID 15987455, 2005). "Impaired ATR signalling has been shown to result in Seckel syndrome, but thus far predisposition to cancer in these patients has not been reported." (PMID 15987455, 2005). "Mutations in ATR and other DNA damage response genes, commonly implicated in Seckel syndrome, may also predispose to vascular fragility and premature atherothrombosis, although this remains speculative." (PMID 41170230, 2025). "Homozygous ATR gene variants are also observed in patients with Seckel syndrome." (PMID 40995433, 2025). "Yet, hypomorphic mutations of the ATR gene lead to the autosomal recessive human Seckel syndrome (ATR-SS), characterized by growth retardation, dwarfism, premature aging, neurological symptoms, such as primary microcephaly, seizure, and intellectual disabilities." (PMID 40105243, 2025). "Mutations in ATR can give rise to Seckel syndrome, a rare genetic condition characterized by dwarfism, microcephaly, radial dislocation, dysplasia, and intellectual disability with decreased life expectancy (report from the National Organization for Rare Disorders, NORD)." (PMID 39456630, 2024). "Full loss of ATR causes cell lethality, probably because of catastrophic chromosome shattering during S-phase, while hypomorphic mutations in ATR cause diseases such as Seckel syndrome." (PMID 38880245, 2024). "Recessive mutations in ATM cause ataxia telangiectasia, a disease characterised by progressive neuronal degeneration; while loss of ATR leads to Seckel syndrome characterised by postnatal dwarfism, microcephaly, intrauterine growth defects, and mental retardation." (PMID 35377872, 2022). "ATR may be more essential than ATM for cell viability since only punctual mutations of ATR have been observed: such ATR mutations cause Seckel syndrome (or microcephalic primordial dwarfism (SCKL))." (PMID 36551628, 2022). "Hypomorphic mutations of ATR cause the human ATR-Seckel syndrome, characterized by microcephaly and intellectual disability, which however suggests a yet unknown role for ATR in non-dividing cells." (PMID 34210973, 2021). "Furthermore, Seckel syndrome (SS) can be caused by mutations in ataxia-telangiectasia and Rad3-related protein (ATR), a kinase critical for activation of the DNA damage checkpoint." (PMID 33477564, 2021). "Several mouse models were made to mimic the ATR-associated Seckel Syndrome." (PMID 32015826, 2020). "The first link between RSR and Seckel syndrome was the identification of mutations in ATR." (PMID 32630049, 2020). "While ATR (NM_001184.3) is an essential gene in mammalian cells, hypomorphic mutations have been implicated in the development of Seckel Syndrome (MIM# 210600), a rare human disorder characterized by severe microcephaly, mental retardation, and developmental defects." (PMID 30199583, 2018). "In this study, we identified two novel compound heterozygous ATR mutations implicated in Seckel Syndrome (Patient P1ATR), one of which, c.151+4A > G (NG_008951.1), is known to affect splicing, while c.4995G > T results in an amino acid change, p.Lys1665Asn, of undetermined pathogenicity." (PMID 30199583, 2018). "One example of this is the ATR-Seckel syndrome that is a result of ATR deficiency." (PMID 30486458, 2018). "However, both exonic point mutations significantly perturb normal splicing of the ATR gene, indicating that ATR-Seckel Syndrome is primarily caused by mutations that affect gene splicing." (PMID 30199583, 2018).